MET (MET proto-oncogene, receptor tyrosine kinase)
Diseases named in the same sentence as MET in open-access papers (continued):
Sharing a sentence is not in itself a finding about the gene and the disease.
renal carcinoma (66 papers, 2010 to 2025). A carcinoma arising from the epithelium of the renal parenchyma or the renal pelvis. "For most MET mutations found in renal cancers, downstream signalling pathway activation has been little or never investigated." (PMID 38652103, 2024). "The definitive link between abnormal MET activation and cancer was confirmed in 1997 through the discovery of MET mutations associated with inherited forms of renal carcinoma." (PMID 38675409, 2024). "Most of the MET mutations recently found associated with resistance to TKIs were already known as MET-activating mutations, notably in renal cancer." (PMID 38652103, 2024). "For instance, the trisomy of chromosome 7 is associated with the overexpression of MET oncogene in renal carcinoma." (PMID 30823889, 2019). "In renal cancers, MET mutations are located mainly in the kinase domain, causing constitutive kinase activity." (PMID 28061464, 2017). "Furthermore, MET expression has been associated with resistance to sunitinib and with more aggressive tumor behavior in renal cancer, becoming an attractive target for the treatment of sunitinib-resistant mRCC patients." (PMID 28423742, 2017). "High MET expression could be associated with poor prognosis in renal cancer, and an in vivo study showed MET phosphorylation enhanced by chronic sunitinib exposure could lead to enhanced migration of affected cells by activating signaling pathways, causing epithelial-mesenchymal transition." (PMID 33374949, 2020). "For instance, copy number variations affect the expression of key protein kinase genes, such as MERTK and MET, which have been shown to correlate with survival outcomes in endometrial cancer and renal cancer." (PMID 40396172, 2025). "A recent study demonstrated that c-MET activation protected renal cancer cells from sorafenib-induced oxidative stress and cytotoxicity through activation of the NRF2-HO-1 antioxidant pathway." (PMID 40369167, 2025). "Second, abnormalities in c‐Met activity and MET gene copy number are also strongly correlated with renal cancer metastasis." (PMID 39092291, 2024). "Functional significance was studied through a co-culture assay with mouse splenocytes and murine renal cancer cells, revealing that c-MET and PD-L1 were significantly up-regulated and co-localized in human renal cancer tissues." (PMID 39664377, 2024). "The enhanced phosphorylation of EGFR, MET, and EPHA2/B1 upon FLCN loss is interesting in light of previous studies that linked these kinases to renal cancer." (PMID 35863698, 2022). "MET protein also plays an important role in the pathogenesis of renal cancer by regulating tumor growth, metastasis and angiogenesis." (PMID 33622324, 2021). "For example, MET expression has been shown to promote upregulation of PD-L1 in renal cancer cells and expression of PD-L1 and PD-L2 are upregulated in MET-amplified gastric and lung tumor cells." (PMID 32659961, 2020). "Renal cancer cells are dependent on Receptor Tyrosine Kinases (RTK) like c-MET for their survival and RTK targeted therapeutics (like, sorafenib, sunitinib, cabozantinib and others) are being used in the first-line of treatment of RCC." (PMID 33332399, 2020). "In our previous reports, we have demonstrated that Honokiol can inhibit renal tumor growth in vivo; and it can also inhibit RTK c-MET-induced growth of renal cancer cells." (PMID 33332399, 2020). "c-MET rescued apoptosis in renal cancer cells, and inhibition of c-MET signaling increased mitochondrial release of cytochrome C and the Bax/Bcl2 ratio." (PMID 28404966, 2017). "Of the deregulated target genes expressed significantly in the current renal cancer specimens, MET and E2F3 were significantly upregulated in RCC compared to noncancer tissues with high diagnostic performance." (PMID 29104726, 2017). "In early reports, increased c-MET expression was found in 87% of renal cell carcinomas and 70% of renal cancer samples from patients." (PMID 29291022, 2017).
renal carcinoma (continued). "To address the clinical relevance of c-MET upregulation during tumor progression, we analysed c-MET in renal cancer patients detecting an increased expression in the bone metastatic lesions by IHC." (PMID 27322553, 2016). "This up-regulation of PD-L1 by c-MET contributes to immune escape mechanisms in renal cancer cells." (PMID 39664377, 2024). "The study suggests that c-MET promotes renal cancer cell survival by regulating HO-1 and PD-L1." (PMID 39664377, 2024). "Exosomal lncARSR could be incorporated into exosomes and transmitted to sensitive cells and then promote sunitinib resistance via competitively binding miR‐34/ miR‐449 to facilitate AXL and c‐MET expression in renal cancer cells." (PMID 32673448, 2020). "Likewise exosome-transmitted lncARSR can promote sunitinib resistance by binding miR-34/miR-449 to facilitate AXL and c-MET expression in renal cancer, acting as a competing endogenous RNA." (PMID 32754302, 2020). "It is believed that lncARSR or AXL/c-MET inhibitors may have curable potential in renal cancer treatment." (PMID 27713133, 2017). "This analysis identified kinases implicated in advanced renal cancer including AXL, ALK1, and MET." (PMID 28418903, 2017). "Qu et fal found that exosome transmitted lnc ARSR functioned as ceRNA sponging miR-34/miR449 that may promote the expression of AXL and c-MET, thus inducing sunitinib resistance in renal cancer." (PMID 27713133, 2017). "Thus, although both types of mutation lead to MET receptor activation, their strict differential distribution among cancers (kinase domain for renal cancer and MET exon 14 for NSCLC) suggests that specific organ contexts favour specific transformation mechanisms." (PMID 38652103, 2024). "Cooperative signaling between MET and EGFR has been observed during kidney development, and aberrant cross-signalling in renal cancer noted to have major implications for therapy." (PMID 38703764, 2024). "Cabozantinib inhibits HGF-induced PD-L1 expression in renal cancer cell-injected mouse models, indicating that it can prevent tumor cell immune escape through HGF/c-MET signaling." (PMID 38289361, 2024). "Knockdown of SOX4 decreased MET, C-myc, cyclinD1, Fra-1, VEGF, and β-catenin expressions in renal carcinomas cells." (PMID 33710813, 2021). "Collectively, we conclude that spheres and CXCR4+MET+CD44+ cells share a gene signature that distinguishes them from controls and characterizes stem cells in renal carcinoma." (PMID 32066735, 2020). "In renal cancer, lncARSR functions as miRNA sponge to competitively bind with miR-34 and miR-449, which can up-regulate AXL/c-MET and activate STAT3, AKT, and ERK signaling." (PMID 31892841, 2020). "Although our patient tested negative for 19 genes known to cause renal cancer syndromes, including FH, VHL, FLCN, and MET, the possibility that the patient has a coexisting autosomal dominant renal cancer syndrome is unlikely but cannot be excluded." (PMID 38802873, 2024). "Overexpression of HIF1A-AS2 increased SOX4, MET, C-myc, cyclinD1, Fra-1, VEGF, and β-catenin expressions in renal cells; knockdown of HIF1A-AS2 decreased SOX4, MET, C-myc, cyclinD1, Fra-1, VEGF, and β-catenin expression in renal carcinomas cells." (PMID 33710813, 2021). "Previous studies reported that mTOR pathway, GSK3 pathway, AKT pathway, EIF4 pathway, MET pathway, NFAT pathway, and FAS pathway acted as essential factors in the development of renal cancer and that CHREBP2 pathway, EDG1 pathway, and CTCF pathway were also cancer-related pathways." (PMID 33102202, 2020). "Similarly to SKOV3 cells, NRF2-silenced renal carcinoma A498 (shNRF2-A498) retained reduced levels of c-MET, EGFR, p-c-MET, p-EGFR, p-AKT, and p-ERK1/2 when compared to those of the A498 control cells." (PMID 29291022, 2017).
renal carcinoma (continued). "Finally, as a standard of care drug in sarcoma and renal carcinoma pazopanib is dosed daily and would thus be likely to block any compensatory survival signaling through PDGFRα/PDGFRβ/FGFR, but not through c-MET or SRC-linked cytokine receptors." (PMID 28146421, 2017). "Exosome from sunitinib-resistant renal cancer cells could transfer lncARSR (lncRNA activated in RCC with sunitinib resistance) to sensitive cells, in which LncARSR competes with miR-34 and miR-449, promotes AXL and c-MET expression, reactivates RTKs, and mediates drug resistance." (PMID 32242003, 2020).
thyroid cancer (59 papers, 2004 to 2025). "Employing RNAi knockout (sgRNA-3165 demonstrated the highest efficiency), we established MET-deficient thyroid cancer cell lines (BCPAP/MET−/− and TPC1/MET−/−) for functional analysis." (PMID 41233563, 2025). "While BRAF and RAS mutations are more common in thyroid cancer, the identification of this rare MET fusion contributes to the limited but growing body of literature on kinase fusion-driven thyroid carcinomas." (PMID 40636652, 2025). "MET proto-oncogene, receptor tyrosine kinase (MET) mutations, frequently associated with familial papillary renal cancer, and mutations associated with other thyroid cancer syndromes were excluded." (PMID 33218058, 2020). "Somatic MET mutations in many other cancers continue to be discovered, such as in gastric, head and neck, liver, ovarian, non-small cell lung, and thyroid cancers." (PMID 28536405, 2015). "In thyroid cancer, MET gene mutations and fusions have also been reported, including PTCs." (PMID 34389035, 2021). "On the other hand, MET predicted as an OCG in thyroid cancer interacted with 19 inhibitors, in accordance with the OCG role of MET." (PMID 40258059, 2025). "In thyroid cancer, integrating ultrasound imaging with the analysis of Gal-3, c-MET, HBME-1, and CK19 expressions has proven helpful in distinguishing between malignant and benign thyroid nodules." (PMID 39664377, 2024). "The clinically most relevant, frequently occurring and selectively targetable, gene alterations in thyroid cancer are the different types of BRAF, RET, NTRK, and MET mutations." (PMID 39409115, 2024). "A series of studies have shown that the overexpression of the MET protein can increase the motility and invasiveness of thyroid cancer cells, leading to early lymphatic metastasis." (PMID 37274228, 2023). "XIST and MET protein compete for the combination of miR-34a, which in turn leads to the progression of thyroid cancer." (PMID 36035993, 2022). "This encompasses both MET and the MAPK and PI3K-Akt pathways, all frequently implicated in thyroid cancer progression and aggressiveness." (PMID 34791326, 2022). "Interestingly, we identified that the DPP4/CTNNB1/MET gene signature was overexpressed in PTCa, which, according to our analysis, is associated with immuno-invasive phenotypes, cancer progression, metastasis, resistance, and unfavorable clinical outcomes of thyroid cancer cohorts." (PMID 35205190, 2022). "LAMB3 was reported to be up-regulated in thyroid cancer and promote papillary thyroid cancer cell migration and invasion by activating the c-MET/AKT signaling pathway." (PMID 36612197, 2022). "The ceRNA activity of XIST versus miR-34a has an oncogenic effect in two different tumors, thyroid cancer and nasopharyngeal carcinoma, due to de-repression of different targets in different cell contexts, i.e., MET and E2F3, respectively." (PMID 35054794, 2022). "Among differentially expressed genes, modulation of FN1, ITGα3, and MET had a significant impact on thyroid cancer cell migration." (PMID 34791326, 2022). "In thyroid cancer, hsa_circ_0074817 targets miR-27a-3p, targeting MET, ABCA1, MMP13, and PLAG1, promoting cell proliferation, invasion, and metastasis in thyroid carcinoma." (PMID 34055888, 2021). "The MET pathway is insensitive to targeted drugs (e.g., BRAF or MEK inhibitors) in refractory thyroid cancer, which can cause a BRAFV600E mutation by activating the downstream PI3K/Akt pathway." (PMID 33489878, 2020). "Another target for HIF-1α is the MET oncogene, which is overexpressed in thyroid cancers, especially medullary thyroid cancer (MTC), thereby promoting angiogenesis, cellular motility, invasion, and metastasis." (PMID 31533238, 2019). "In this study, among a panel of 11 human thyroid cancer cell lines, the amplification and overexpression of the MET gene in the TTA1 ATC-derived cell line was described." (PMID 31040922, 2019).
thyroid cancer (continued). "The expression of MET mRNA was analyzed in eleven thyroid cancer cell lines, including 3 PTC cell lines (TPC1, KTC1 and BCPAP) and 8 ATC cell lines (HTh74, TTA1, ACT1, CAL62, C643, SW1736, HTh104 and 8505C)." (PMID 31040922, 2019). "FISH experiments demonstrated that TTA1 cells possessed a high copy number of the MET gene, compared to three thyroid carcinoma cell lines (BCPAP, HTh74 and SW1736), which expressed low levels of MET." (PMID 31040922, 2019). "XIST serves as a ceRNA for miR-34a through sponging miR-34a, competing with MET for miR-34a binding, and finally modulating thyroid cancer cell proliferation and tumor growth." (PMID 30463570, 2018). "Contrary to miR-34a, MET mRNA expression and protein level were significantly increased in thyroid cancer tissue samples; moreover, MET expression was positively correlated with XIST, whereas negatively correlated with miR-34a expression." (PMID 30463570, 2018). "Eleven of 18 BRAFV600E-specific genes were previously reported as related to thyroid cancer, with 6 documented as associated with BRAF mutation (DCSTAMP, MET, FN1, DIO1, EPHA2, and ERBB3)." (PMID 26625260, 2015). "MET overexpression in thyroid cancer has been identified in a number of studies and this molecule was 2.3-fold higher expressed in our study in BRAFmut compared to BRAFwt PTCs which is in accordance with another survey." (PMID 25922907, 2015). "MET p.T992I is also reported in the germline DNA of 4% of thyroid cancers, one endometrial and two melanoma cancer cases, and one normal individual." (PMID 21970370, 2011). "This makes c-MET an attractive target for preoperative cytological diagnostics in thyroid cancer." (PMID 40346322, 2025). "Notably, elevated MET expression drives metastatic progression in thyroid cancer, a finding corroborated by clinical specimen analysis revealing a significant correlation between high MET expression and metastatic potential (P = 0.0002)." (PMID 41233563, 2025). "Together, these results establish that MET is essential for thyroid cancer cell migration." (PMID 41233563, 2025). "This is amplified by the fact that the fusion proteins originating from the majority of the detected driver mutations, namely those of RET, NTRK3, CCDC6 (when co-occurs with RET), and MET, can be effectively targeted with small tyrosine kinase inhibitors in thyroid cancer." (PMID 39409115, 2024). "Moreover, the oncogene MET, which is frequently up-regulated in thyroid cancer, is also a predicted miR-34a-5p target." (PMID 32163919, 2020). "Notably, LRRK2 amplification has been observed to be of indirect oncogenic potential in papillary renal cell carcinoma and thyroid carcinomas trough MET signaling." (PMID 32722212, 2020). "MET may also be exhibited to be overexpressed in PTC with extremely limited investigation done in thyroid carcinoma." (PMID 27703281, 2016). "Indeed, non-MET related effects of crizotinib were reported to contribute to the cell-cycle arrest and cytotoxicity observed in thyroid cancer cells and inhibition of other RTKs, independently of ALK expression and activity, was recently observed in RMS cells." (PMID 26445453, 2015). "Thus, inhibiting MET pathway may become a new strategy for the treatment of dedifferentiation of thyroid cancer." (PMID 33489878, 2020). "Consequently, we suspect that the miR-146b-3p/MUC20/MET signaling pathway the targeting relationship of might play a role in the redifferentiation of iodine-refractory thyroid cancer." (PMID 33489878, 2020). "In thyroid carcinoma, XIST acts as a ceRNA sponging miR-34a and competes with MET for miR-34a binding." (PMID 39030557, 2024). "It was also found that the POU4F1 suppressed tumor metastasis via c-MET/STAT3 inhibition and EMT suppression in thyroid cancer." (PMID 34970597, 2021). "Other studies have shown that combined treatment with MET and MAPK pathway inhibitors can effectively inhibit the proliferation and differentiation of thyroid cancer cells." (PMID 33489878, 2020).
thyroid cancer (continued). "MET is a receptor tyrosine kinase that promotes cell proliferation through PI3K/AKT signaling and miR-34a is considered to be a tumor suppressor targeting MET, thus XIST promotes the proliferation of thyroid cancer by down-regulating miR-34a and increasing MET." (PMID 39030557, 2024). "MET is an established oncogene known to be overexpressed in thyroid cancer, and this specific alteration was not reported as a single nucleotide polymorphism (SNP), suggestive of a mutation." (PMID 34389035, 2021). "And the BCPAP thyroid cancer cell line, used as a negative control which expresses a low level of MET, displayed a weak cell proliferation inhibition with a 2500 nM IC50." (PMID 31040922, 2019). "In 77 paired thyroid cancer and non-tumor tissues, MET mRNA expression was also remarkably up-regulated, consistent database results." (PMID 30463570, 2018). "In thyroid cancer, XIST may serve a ceRNA for miR-34a to compete with MET for miR-34a binding, thus affecting thyroid cancer cell proliferation and tumor growth." (PMID 30463570, 2018). "Notably, thyroid cancers have the highest frequency of recurrent kinase fusions (63/498, 13%), and all fusion events including ALK, BRAF, MET, NTRK1, NTRK2, RAF1 and RET are mutually exclusive in this cancer type." (PMID 25204415, 2014). "Moreover, we examined whether coordinate signalling by ITGA3 and MET regulates the activation of PI3K/AKT signalling and ERK signalling, as MET and ITGA3 were both enriched in the same KEGG pathways in the thyroid cancer cluster." (PMID 40138447, 2025). "In conclusion, our present findings show that anti-miR-146b-3p could restore radioiodine uptake in dedifferentiated thyroid cancer by up-regulating NIS expression and translocation to the cell membrane in vitro by targeting MUC20 through MET Signaling pathways." (PMID 33489878, 2020). "Therefore, it indicated that miR-146b-3p/MUC20/MET pathways may play important role in NIS expression and radioiodide uptake by inhibition of miR-146b-3p expression to induce redifferentiation of dedifferentiated thyroid cancer cells." (PMID 33489878, 2020). "However, cellular models of MET-overexpressed thyroid cancers were not yet described and the biological and therapeutic impacts of constitutively activated MET signaling were not directly investigated in thyroid cancers." (PMID 31040922, 2019).